FOXA1 (forkhead box A1)
Diseases named in the same sentence as FOXA1 in open-access papers (continued):
Sharing a sentence is not in itself a finding about the gene and the disease.
prostate tumors (27 papers, 2010 to 2025). "In the Asian population, however, FOXA1 mutations are detected in over 40% of primary prostatic tumors, surpassing ETS fusions to become the predominant driver alteration in this patient ethnicity." (PMID 40570057, 2025). "This region has been identified as one of six cis-regulatory elements in the FOXA1 regulatory plexus harboring somatic single-nucleotide variants in primary prostate tumors." (PMID 37868033, 2023). "The FOXA1 gene is recurrently mutated in prostate tumors and FOXA1 mutations define a specific molecular subtype in the TCGA cohort." (PMID 36212399, 2022). "Analysis of large tumour cohorts such as The Cancer Genome Atlas (TCGA) revealed that tumours with FOXA1 mutations have a higher AR transcriptional signature compared to normal tissues and other prostate tumour subtypes." (PMID 32946061, 2021). "FOXA1 pioneer transcription factor is recurrently mutated in primary and metastatic prostate tumors." (PMID 31974375, 2020). "Collectively, our results identify cis-regulatory elements within the FOXA1 plexus mutated in primary prostate tumors as potential targets for therapeutic intervention." (PMID 31974375, 2020). "Recurrently mutated in primary and metastatic prostate tumors, FOXA1 encodes a pioneer transcription factor involved in disease onset and progression through both androgen receptor-dependent and androgen receptor-independent mechanisms." (PMID 31974375, 2020). "Here, we identify a set of six cis-regulatory elements in the FOXA1 regulatory plexus harboring somatic single-nucleotide variants in primary prostate tumors." (PMID 31974375, 2020). "However, Skp2 loss significantly increased Foxa1 levels in prostate tumors of Ptenpc−/−; Trp53pc−/−; Skp2+/− and Ptenpc−/−; Trp53pc−/−; Skp2−/− mice in a dose‐dependent manner, indicating an essential role for Skp2 in Foxa1 regulation." (PMID 37491794, 2023). "Importantly, FOXA1 protein level in primary prostate tumors has a significant association with the disease outcome; high FOXA1 level is associated with poor prognosis, whereas low FOXA1 level, even in the presence of high AR expression, predicts good prognosis." (PMID 23192763, 2013). "We mapped FOXA1 alterations found in primary prostatic tumors, metastatic sites, or histologic NEPC based on the protein domains." (PMID 39745364, 2025). "A previous report indicated that 41% of prostate tumors from a Chinese cohort harbored FOXA1 alterations." (PMID 39745364, 2025). "Fourteen of the 47 prostate tumor-specific ARBSs were co-occupied by both FOXA1 and HOXB13, implying that FOXA1 and HOXB13 also contribute to the regulation of these DEGs in PCa." (PMID 40525903, 2025). "Worthy of note, Skp2 ablation with concurrent enhanced levels of Foxa1 in Ptenpc−/−; Trp53pc−/−; Skp2−/− mice resulted in decreased tumor burden by suppressing prostate tumor proliferation." (PMID 37491794, 2023). "The cistromes of the forkhead box protein A1 (FOXA1) and homeobox protein HOXB13, two essential pioneer factors associated with the AR and AR-V7, are also altered in prostate tumors." (PMID 36768610, 2023). "We then proceeded to investigate the effects of Skp2 KO in the ubiquitin‐mediated regulation of Foxa1 in prostate tumors of conditional knockout (pc−/−) Ptenpc−/−; Trp53pc−/−; Skp2−/− mutant mice." (PMID 37491794, 2023). "Targeting post‐translational regulatory mechanisms for FOXA1 through SKP2 inhibition (SZL P1‐41) reduced prostate tumor proliferation, and restored luminal phenotypes and FOXA1 levels, supporting enhanced therapeutic sensitivity in advanced stages of PCa." (PMID 37491794, 2023). "Our results, combined with the analysis of the TCGA data set, show that prostate tumours with Gleason pattern 4 share a common transcriptional regulatory programme defined by an enrichment of FOXA1, HOXB13 and CDX2 binding sites." (PMID 34911933, 2021).
prostate tumors (continued). "In prostate tumours, FOXA1 is capable of reprogramming AR binding sites and drives oncogenic programs along with transcription factor HOXB13." (PMID 32946061, 2021). "Tandem duplications within the FOXA1 locus account for 70% of all SVs identified across >1,400 primary and advanced prostate tumours." (PMID 32946061, 2021). "These efforts highlight that the cis-regulatory plexus of FOXA1 can be recurrently hijacked in prostate tumours to drive aberrant gene expression and disease progression." (PMID 32946061, 2021). "Using the same data set we also find that FOXA1 is the most highly expressed out of 41 other Forkhead Box (FOX) factors in prostate tumors." (PMID 31974375, 2020). "We extended this concept with SNVs identified from primary prostate tumors mapping to FOXA1 plexus CREs." (PMID 31974375, 2020). "According to the Cancer Genome Atlas (TCGA) gene expression datasets, FOXA1 is also expressed higher in prostate tumor tissue samples than normal tissue samples (p value < 4.24e-03, Student’s t-test)." (PMID 31515496, 2019). "SNVs in FOXA1 occurred more frequently in breast and prostate tumours derived of older individuals." (PMID 35017538, 2022). "We found low-grade prostate tumours were significantly enriched for the AP-1 family of TF binding sites (JUN, JUNB, JUND and FOS, FOSB and FRA1, and the closely related activating TFs: ATF and CREB), in contrast to high-grade prostate tumours that were enriched for FOXA1, HOXB13 and CDX2." (PMID 34911933, 2021). "As a whole, our findings in conjunction with recent reports suggest that CREs involved in the transcriptional regulation of FOXA1 may be hijacked in prostate tumors through various types of genetic alterations." (PMID 31974375, 2020). "We find that FOXA1 mRNA is consistently the most abundant in prostate tumors compared with 25 other cancer types across patients, ranking in the 95th percentile for 492 of 497 prostate tumors profiled in TCGA." (PMID 31974375, 2020). "Notably, genes associated with luminal differentiation (i.e. FOXA1, TMPRSS2, HOXB13, KLK3, KLK2) had significantly reduced expression in the ‘low’ NKX3.1 prostate tumors." (PMID 30266798, 2018). "Thus, regardless of mutation origin, perturbation of the FOXA1/AR-mediated regulatory program emerges as a unifying mechanism that drives prostate tumor formation and progression." (PMID 41468516, 2025). "In addition, high expression of FOXA1 is commonly observed in prostate tumors." (PMID 20169163, 2010). "These lesions expressed the V5-tagged FOXA1 R265–71del mutant along with AR and CK8 luminal markers, akin to primary prostatic tumors detected in humans." (PMID 40570057, 2025). "The shift from FOXA1 to FOXA2 expression represents a notable marker of lineage plasticity and disease progression within prostate tumors, highlighting a transition toward a more aggressive phenotype." (PMID 39470735, 2024). "Of the 13 prostate tumor-specific ARBSs, five were co-occupied by both FOXA1 and HOXB13, suggesting that FOXA1 and HOXB13 also contribute to the regulation of our DE-lncRNAs in PCa." (PMID 37140987, 2023). "We observe that each Gleason pattern 4 tumour is enriched for FOXA1, HOXB13 and CDX2 binding motifs, suggesting that higher-grade prostate tumours converge on the same trans-regulatory landscape." (PMID 34911933, 2021). "We anticipate that there is a similar synergy between FOXA1, HOXB13 and CDX2 TFs in remodelling the chromatin structure in high-grade prostate tumours." (PMID 34911933, 2021). "In line with this, a set of reprogrammed AR‐binding regions characterized by FOXA1 and HOXB13 colocalization is acquired in prostate tumors." (PMID 32333502, 2020).
prostate tumors (continued). "In parallel to our observations, we found FOXA1, HOXB13 and CDX2 to be highly enriched in prostate tumours with primary Gleason pattern 4 (Gleason score 4 + 4 and 4 + 5 patients) as compared to tumours that are predominantly Gleason pattern 3 (Gleason score 3 + 4)." (PMID 34911933, 2021). "AR, FOXA1, and GRHL2 (a co-regulator of AR) are key TFs that promote prostate tumor progression." (PMID 31515496, 2019). "Therefore, we investigated the AR, FOXA1, and HOXB13 binding in the regulatory regions (−15 kb/+2 kb from TSS) of the DEGs by utilizing previously published prostate tumor and prostate normal tissue-specific AR-binding sites (ARBSs) and FOXA1- and HOXB13-binding sites in PCa tumor samples." (PMID 40525903, 2025). "Pioneer transcription factors, including FOXA1, HOXB13, and GATA2, as well as the transcription factor ERG, have prominent roles to play in earlier, hormone-sensitive stages of the disease and in CRPC where AR signaling remains a mainstay of prostate tumor growth." (PMID 36212399, 2022). "In non-transformed prostate cell line, FOXA1, when co-expressed with HOXB13, reprograms genome-wide AR occupancy to an aggressive prostate tumour model." (PMID 39796635, 2024).
colon carcinoma (20 papers, 2010 to 2025). "Like RBM47, FOXA1 is highly expressed in normal colon epithelial cells, but significantly down-regulated in colon cancers." (PMID 41335176, 2025). "Transwell and scratch assays demonstrated that FOXA1 promoted the invasion and metastasis of colon cancer cells." (PMID 39665272, 2025). "Like RBM47, FOXA1 expression was consistently and significantly down-regulated in colon cancers when compared to adjacent normal colon tissue." (PMID 41335176, 2025). "The effect of FOXA1 on the function of colon cancer cells was examined through lentivirus‐mediated inhibition of FOXA1 expression." (PMID 39665272, 2025). "qRT‒PCR revealed that FOXA1 was most considerably decreased in colon cancer cells after Lyn knockdown." (PMID 39665272, 2025). "In summary, the Lyn/RUVBL1 complex regulates AA metabolism in colon cancer cells by upregulating COX2 through FOXA1." (PMID 39665272, 2025). "In human gastric cancer, down‐regulation of FOXA1 by the E3 ligase ZFP91 has been associated with promotion of chemoresistance, while in colon cancer down‐regulation of FOXA1 via NEDD4 promoted EMT and metastasis." (PMID 37491794, 2023). "Another study in colon cancer tissues demonstrated that NEDD4 promotes the progression of cancer by activating FOXA1 ubiquitination in conjunction with the inhibition of miRNA-340-5p and the overexpression of ATF1." (PMID 36293239, 2022). "We next focused directly on β-catenin, since it has been reported as necessary for SOX17 transcription of FOXA1 and associated with regulating the transcription factor ZEB-1 by the tight junction protein Claudin-1 in colon cancer cells." (PMID 33669586, 2021). "High levels of Foxa1 expression were observed in poorly differentiated colon cancer, and Gata6, the colon homolog of Gata4, participates in the regulation of stemness by preventing Bmp4-induced differentiation in Wnt-driven colon cancer." (PMID 33349639, 2020). "This is consistent with studies showing that the forkhead TFs FOXO3 and FOXA1, which have a 2 and 2.4-fold increase in gainability in colon/rectum cancer respectively, promote colon cancer proliferation." (PMID 33077858, 2020). "The human shMLL1 colon cancer cells showed a decrease of the expression of FOXA1 and the GATA4 colon homolog GATA6, which we had identified as Mll1-regulated genes in murine β-catGOF; Mll1−/− stem cells." (PMID 33349639, 2020). "By increasing enhancer activity, FOXA1 can positively regulate CYR61 expression to promote colon cancer cell migration and metastasis." (PMID 31118064, 2019). "To verify whether FOXA1 could promote colon cancer cells metastasis by up-regulating CYR61 expression in vivo, we constructed mouse models by tail vein injection of cancer cells and observing lung metastases." (PMID 31118064, 2019). "However, the molecular mechanisms by which FOXA1 is activated and induced to bind to DNA elements in specific colon cancer subtypes remain to be fully understood." (PMID 31118064, 2019). "When Lyn was overexpressed in colon cancer cells, Lyn facilitated COX2, whereas the inhibition of FOXA1 reversed this effect." (PMID 39665272, 2025). "A recent study showed that overexpression of FOXA1 reduces the proliferation induced by NEDD4 upregulation and promotes apoptosis in Caco-2/LoVo colon cancer cells." (PMID 36293239, 2022). "We then asked whether FOXA1 and FOXA2 ChIP-seq peak distribution deviated from this pattern at the colon cancer EMT signature genes introduced above." (PMID 29155818, 2017). "Moreover, relatively high coexpression scores were also observed for FOSL2/KLF6, FOSL2/RUNX2 and GRHL2/FOXA1, suggesting that the DETFs related to H3K23su DERs might work together and be responsible for 5-FU resistance in HCT15 colon cancer cells." (PMID 40082673, 2025).
prostate adenocarcinoma (20 papers, 2013 to 2026). "Further loss of the retinoblastoma protein (RB1), along with telomerase activation and frequent Forkhead Box A1 (FOXA1) mutation, leads to the development of prostate adenocarcinoma from the advanced PIN lesion." (PMID 32957478, 2020). "We compared FOXA1 and NKX3.1 expression in benign prostatic glands and prostatic adenocarcinoma; FOXA1 immunostaining demonstrated a similar nuclear staining pattern to NKX3.1 and a high sensitivity for prostatic adenocarcinoma." (PMID 42098986, 2026). "We explored genetic alterations in FOXA1 using cBioPortal and observed that patients in prostate adenocarcinoma and non-small-cell lung cancer have high genetic alterations of FOXA1." (PMID 36393971, 2022). "FOXA2 was expressed only in the endometrial cell line, while FOXA1 was expressed only in the prostate cell line, in agreement with the tissue expression patterns and that most prostatic adenocarcinomas and LNCaP are of secretory (i.e., luminal) cell origin." (PMID 35703180, 2022). "While FoxA1 was low expressed in kidney chromophobe and uveal melanoma, the expression was higher in prostate adenocarcinoma and breast invasive carcinoma when compared to cholangiocarcinoma." (PMID 32151057, 2020). "We conducted an analysis of TCGA primary prostate adenocarcinoma (PRAD) mRNA-seq data to compare two groups: a FOXA1 mutant group and a mutation-negative (control) group." (PMID 37958805, 2023). "In particular, we found none of the ERG-family fusion genes or structural variants, no SPOP mutations, no further FOXA1 mutations, and none of the recurrent whole chromosomal aneuploidies seen in prostate adenocarcinoma." (PMID 33657416, 2021). "The role of FOXA1 in the transition from prostate adenocarcinoma (PRAD) to NEPC seems to contradict the role of maintaining NE gene expression in NEPC." (PMID 38605023, 2024).
colorectal cancer (17 papers, 2015 to 2025). A primary or metastatic malignant neoplasm that affects the colon or rectum. "FOXA1 expression was also significantly higher in colorectal cancer tissues derived from TCGA datasets and was linked to worse prognosis in the R2 database." (PMID 35498155, 2022). "Based on data from public datasets, the transcription factor CEBPB is more valuable than FOXA1 in evaluating the prognosis of colorectal cancer, so we further explored the regulatory relationship between CEBPB and SERPINA1." (PMID 38710698, 2024). "Here we used a public colorectal cancer dataset to analyze the prognostic significance and clinical relevance of FOXA1 and CEBPB." (PMID 38710698, 2024). "KM curves showed that FOXA1 expression was related to OS in GSE17537 colorectal cancer patients but the curves crossed (P = 0.016)." (PMID 38710698, 2024). "FOXA1—FOXA1 inhibits anoikis (cell death upon detachment from the extracellular matrix) in colorectal cancer." (PMID 38304289, 2023). "A direct link between SNAI1 and FOXA1 is thus proposed based on reports from colorectal cancer where SNAI1 can directly repress the FOXA1 gene, and tumor cells acquire mesenchymal features upon FOXA1 knockout." (PMID 36171192, 2022). "Through down-regulating FOXA1 and up-regulating TGFB3, miR-93-5p in exosomes of tumor-associated fibroblasts enhances radiation resistance of colorectal cancer cells." (PMID 34130593, 2021). "For example, miR-760 boosts TRAIL sensitivity in non-small cell lung cancer through reducing the protein FOXA1; miR-760 suppresses human colorectal cancer growth by targeting BATF3/AP-1/cyclinD1 signaling." (PMID 31693728, 2019). "Interestingly, re-annotation of the significantly enriched peaks obtained from SNAI1 ChIP-sequencing analysis in human colorectal cancer cells showed that SNAI1 occupies the proximal promoter region of FOXA1." (PMID 36171192, 2022). "As SOX17 associated with β-catenin has been shown to regulate the transcription of FOXA1 in endodermal and colorectal cancer cells, and β-catenin is reportedly influenced by JAM-A expression, we investigated whether JAM-A expressional alterations would change SOX17 expression." (PMID 33669586, 2021). "In colorectal cancer, NEDD4L suppresses tumorigenesis by promoting the ubiquitin-mediated degradation of phosphatase and tensin homolog (PTEN) and forkhead box A1 (FOXA1)." (PMID 41561975, 2025). "Based on the colorectal cancer dataset GSE19860, Spearman’s method was used to analyze the correlation between SERPINA1 and FOXA1 (r = 0.19, P = 0.23) and the correlation between SERPINA1 and CEBPB (r = 0.45, P = 0.0034)." (PMID 38710698, 2024). "Compared to KIPAN tumors in stage M0, KIPAN tumors in stage M1 have significantly higher expression of FOXA1; while in colorectal cancer, COAD and COADREAD, the expression level of FOXA1 in tumors in stage M1 is significantly down-regulated." (PMID 39440050, 2024). "Based on the TCGA-CRC dataset, FOXA1 expression was significantly lower than that in adjacent non-tumor tissue (P < 0.001), and KM curves showed that FOXA1 expression was not related to OS in TCGA colorectal cancer patients (P = 0.045)." (PMID 38710698, 2024). "Expression of FOXA1 was correlated with earlier pathological stages of colorectal cancer (P < 0.001), and was not correlated with T stage (P > 0.05), but was correlated with N stage (P < 0.001) and M stage (P < 0.001)." (PMID 38710698, 2024).
colorectal cancer (continued). "Because the expression of FOXA1 and CEBPA was not induced by the knockdown of β-catenin in colorectal cancer cells, transcription factors that are expressed in liver tissues might be involved in the regulation of CEBPA and/or FOXA1 expression." (PMID 38684876, 2024).